DESI1 (desumoylating isopeptidase 1)
Description:
Protease which deconjugates SUMO1, SUMO2 and SUMO3 from some substrate proteins. Has isopeptidase but not SUMO-processing activity (By similarity). Desumoylates ZBTB46 (By similarity). Collaborates with UBQLN4 in the export of ubiquitinated proteins from the nucleus to the cytoplasm. Exhibits palmitoyl protein thioesterase (S-depalmitoylation) activity towards synthetic substrates 4-methylumbelliferyl-6-S-palmitoyl-beta-D-glucopyranoside and S-depalmitoylation probe 5 (DPP-5).
Synonyms: DeSI-1; POST; FAM152B; PPPDE2; D15Wsu75e; DJ347H13.4
Tractability: PROTAC: ubiquitination databases record sites on it.
Gene: Protein-coding gene on chromosome 22 (41,598,028 to 41,621,081, reverse strand). Ensembl gene ENSG00000100418.
Subcellular location: Cytoplasm; Nucleus
Subcellular location (Human Protein Atlas): Cytosol; Cytokinetic bridge
Gene Ontology:
Molecular function: importin-alpha family protein binding; long-chain fatty acyl-CoA hydrolase activity; palmitoyl-(protein) hydrolase activity; protein binding; deSUMOylase activity; hydrolase activity; identical protein binding; peptidase activity
Biological process: protein export from nucleus; regulation of proteasomal ubiquitin-dependent protein catabolic process; macromolecule depalmitoylation; protein desumoylation
Cellular component: cytoplasm; cytosol; nucleus; protein-containing complex
Genetic constraint (gnomAD): Loss-of-function variants: 17 observed, 22.82 expected, observed/expected ratio (o/e) 0.75, 90% interval 0.51 to 1.12. The upper end of that interval is the gene's LOEUF score, 1.12, which puts it in group 4 of 6, group 1 being the genes least tolerant of losing a copy. Missense variants: 177 observed, 217.27 expected, observed/expected ratio (o/e) 0.81, 90% interval 0.72 to 0.92. Synonymous variants: 92 observed, 87.58 expected, observed/expected ratio (o/e) 1.05, 90% interval 0.89 to 1.25.
Homologues: Orthologues: chimpanzee DESI1 (100% identical), macaque DESI1 (100% identical), guinea pig DESI1 (97% identical), mouse Desi1 (97% identical), pig DESI1 (85% identical), dog DESI1 (76% identical), rat Desi1 (72% identical), zebrafish desi1a (70% identical), zebrafish desi1b (69% identical), tropical clawed frog desi1 (68% identical), Drosophila melanogaster CG6972 (23% identical). Paralogues in human: DESI2 (30% identical).
Diseases named in the same sentence as DESI1 in open-access papers:
DESI1 is named in the same sentence as 6 diseases in open-access papers, as found by Europe PMC text mining. Sharing a sentence is not in itself a finding about the gene and the disease. The quoted sentences say what the papers report.
melanoma (1 paper, 2024). A malignant, usually aggressive tumor composed of atypical, neoplastic melanocytes. "Pan‐cancer and some cancer types, including pancreatic cancer, melanoma, and thyroid cancer, showed DESI1 upregulation in cancer cells compared with normal cells." (PMID 39698932, 2024).
thymic lymphoma (1 paper, 2025). "C8, C11, C7, and C18 were proximal to double‐positive T cells, representing thymic lymphoma characterised by elevated expression levels of genes like Notch1, Hes1 and Desi1,72, 73 along with markers associated with thymic T‐cell development such as Rag1/2, Xrcc6 and Dntt74." (PMID 40887856, 2025).
cancer (1 paper, 2024). A tumor composed of atypical neoplastic, often pleomorphic cells that invade other tissues. "Kaplan–Meier survival analysis revealed that an increased expression of DESI1 is associated with a poorer prognosis in patients with these cancer types." (PMID 39698932, 2024). "The TCGA database showed that both decreased and increased DESI1 expression levels are associated with poor prognosis in patients with certain cancer types." (PMID 39698932, 2024). "Data from the TCGA database revealed that deregulation of DESI1 is associated with a poorer cancer patient prognosis." (PMID 39698932, 2024). "DESI1 is required for the activity of FoxM1 in the transcription of mitotic regulators including Aurora B. Lower levels of DESI1 in cancer cells are associated with poorer prognosis of patients with endometrioid cancer and a decrease in sensitivity against microtubule‐targeting agents." (PMID 39698932, 2024). "DESI1 expression levels are associated with the prognosis of patients with cancer." (PMID 39698932, 2024). "This suggests that the use of vincristine for cancer cells with decreased levels of DESI1 may increase the risk of cancer development and malignancy via chromosomal instability." (PMID 39698932, 2024). "Similar to SENP family proteins, deregulation of DESI1 is hypothesized to be associated with cancer, but the role of DESI1 in most cellular events remains largely unexplored." (PMID 39698932, 2024). "The results of this study indicate that DESI1 is a novel regulator of cell division, catalyzing deSUMOylation, and that its deregulation may be associated with cancer by causing failure in cell division." (PMID 39698932, 2024). "Our findings identified DESI1 as a novel regulator of cell division and a factor affecting cancer chemotherapy." (PMID 39698932, 2024). "Given that proper chromosome segregation is crucial to preventing cancer development and malignancy, we examined the role of DESI1 in M‐phase progression." (PMID 39698932, 2024). "The chromosome segregation defect caused by DESI1 knockdown suggests a role for chromosomal instability in the development of this cancer with low DESI1 expression levels." (PMID 39698932, 2024). "Additionally, DESI1 affects the sensitivity of cancer cells to anticancer agents whose cytotoxicity is dependent on the SAC activity." (PMID 39698932, 2024). "Overexpression of DESI1 is observed in certain cancer types." (PMID 39698932, 2024).
DESI1 also shares sentences with these, for which no sentence is quoted: pancreatic cancer (1 paper); thyroid cancer (1); tumor (1).